EGFR (epidermal growth factor receptor)
Diseases named in the same sentence as EGFR in open-access papers (continued):
Sharing a sentence is not in itself a finding about the gene and the disease.
tumor (continued). "For example, IF staining of EGFR and hnRNP A3 in tumor and adjacent normal tissues obtained from NSCLC patients revealed that hnRNP A3 and EGFR exhibited elevated colocalization in tumor sections compared with adjacent normal sections." (PMID 32321917, 2020). "We recently demonstrated that in EGFR-mut and EGFR-TKI resistant NSCLC preclinical models, mTORC2 is critically required for epithelial-mesenchymal transition (EMT) and tumor growth in the mouse brain in a brain-borne microglia/macrophage-dependent manner." (PMID 32923403, 2020). "In both of these cases we see distinct regions with EGFR and PDGFRA amplification forming in the simulated tumours of equal proportion." (PMID 33120534, 2020). "Increased tumour size, less necrosis and reduced numbers of CD8+ Ki67 + and CD4+ IFN-γ+ cells were observed in mice injected with EGFR-19 del LLC EVs compared to wild-type EVs." (PMID 33143170, 2020). "Further, there is a statistically significant association between the CK5/6 and/or EGFR expression and the presence of tumor necrosis, which provide the clue of exploratory study on the molecular mechanisms of how CK5/6 and EGFR impact on prognosis of TNBC." (PMID 33552956, 2020). "In summary, GC1118 exerted a potent anti-tumor effect on GBM tumors in PDX models, and its therapeutic efficacy was especially pronounced in the tumors with high EGFR amplification." (PMID 33142709, 2020). "Treatments with ABT-414, ABBV-221 and ABBV-322 resulted in significant tumor growth inhibition in EGFR-overexpressing cell lines in vitro, as well as in their derived xenografts and PDX models with high EGFR and mAb806 epitope expression." (PMID 33023139, 2020). "EGFR regulates several signaling transduction cascades such as MAPK, JNK, and Akt signaling pathways, leading to tumor cell proliferation, cell cycle progression, angiogenesis, and metastasis." (PMID 32206449, 2020). "The overexpression of EGFR is more commonly found in the primary tumor stages III/IV than I/II, and has been previously identified as a predictor of tumor recurrence." (PMID 32093644, 2020). "Moreover, even after entering the tumor microenvironment, killer T cells may have reduced killing potential due to hypoxic conditions generated because of IDH variants and the heterogeneity of EGFR mutations." (PMID 32765489, 2020). "Activation of EGFR in cancer cells can activate several linear pathways, and the PI3K/AKT axis, one of the major downstream pathways, participates in regulating tumour cell proliferation, growth, survival and angiogenesis." (PMID 31993801, 2020). "On the other hand, the GAS6-independent pathway involves EGFR that activates AXL, which finally unleashes Akt transcription and produces an increase of tumor cell proliferation and migration." (PMID 33138097, 2020). "EGFR inhibitors have also been found to induce autophagy in non-small cell lung cancer (NSCLC) and many other tumor cells." (PMID 33055358, 2020). "The expression of PD-L1 was induced by EGFR and JAK2/STAT1, while the inhibition of JAK2 repressed the upregulation of PD-L1 in tumor cells and enhanced their immunogenicity." (PMID 33603661, 2020). "A study has found that DOK2 is a tumor suppressor gene in LUAD and that knocking out Dok2 in mice accelerates lung tumorigenesis induced by oncogenic EGFR." (PMID 32775050, 2020). "Patients whose tumor showed a strong pTyr-RTK signal, pTyr-EGFR for example, would likely respond to the corresponding inhibitor, e.g. Necitumumab, a WT EGFR inhibitor." (PMID 32555693, 2020). "In high PDIA3 expression samples, frequently amplified genomic peaks were detected in oncogenic drivers, including PDGFRA, EGFR and CDK4; in addition, tumor suppressor genes, such as CDKN2A/CDKN2B and PTEN were observed a deletion peak." (PMID 32687065, 2020).
tumor (continued). "To address the functional role of the putative EGFR–hnRNP A3 interaction in the nucleus, we used immunohistochemistry (IHC) to detect the expression levels of hnRNP A3 and EGFR in 15 NSCLC tumor tissues and paired adjacent normal sections." (PMID 32321917, 2020). "Specifically, for the 41 patients with positive PD-L1 status (tumor proportion score (TPS) ≥ 1%), the patients with high EGFR-DLS had a low DCB rate of 54.54% and a high hyperprogression rate of 18.18% vs 76.67% and 6.67% in the patients with low EGFR-DLS." (PMID 33067442, 2020). "Inhibition of EGFR by TKI, erlotinib, disrupts the interaction between Bim and Mcl-1 and sensitizes tumor cells to ABT-737 treatment." (PMID 32276600, 2020). "TESC induced by the TGFα/EGFR/signal transducer and activator of transcription 3 (STAT3) signaling pathway promotes cell proliferation and tumor growth in vivo and in vitro by increasing the expression of forkhead box M1 (FOXM1)." (PMID 32708604, 2020). "EGFR is involved in the acquisition of self-sufficient growth-stimulatory signaling, while ITGB4 promotes the tumor ability for invasion and metastasis." (PMID 32886718, 2020). "Tumor cell lines that upregulate CLCA2 also upregulate TMEM16A and EGFR, suggesting TMEM16A and CLCA2 are part of an EGFR-promoting axis." (PMID 32575848, 2020). "EPGN is a ligand of epidermal growth factor receptor (EGFR), which was known to be related with EMT and tumor metastasis." (PMID 33318296, 2020). "In this study, we present an EGFR- and ALK-negative advanced NSCLC case for which we conducted comprehensive tumor genomic profiling to identify potentially actionable alterations." (PMID 32190395, 2020). "Curcumin also downregulated the expression of the AR protein and NKX3.1 tumor suppressor, as well as PSA levels, Erb-B2 Receptor Tyrosine Kinase 2 (ERBB2), and epidermal growth factor receptor (EGFR)." (PMID 33182828, 2020). "We further demonstrated that CAFs affect proliferation, EGFR expression and to some extent, the EMT and CSC phenotype of HNSCC tumor cells." (PMID 33353547, 2020). "In the application of UniCAR to the bivalent epidermal growth factor receptor (α-EGFR-EGFR), the TM that retargeted UniCAR-T to the tumor cells with low-expressing EGFR has proved to be effective." (PMID 32964055, 2020). "Although the molecular basis for HNSCC is complicated, the epidermal growth factor receptor (EGFR) is known to play a vital role in HNSCC carcinogenesis and tumor progression." (PMID 32929368, 2020). "Despite high tumor selectivity, we recently discovered that the intracellular uptake of Cet-BPD is six fold less than that of free BPD in EGFR-overexpressing cancer cells, significantly reducing the anti-cancer phototoxicity by 20-fold." (PMID 31898555, 2020). "In mice implanted with MIA PaCa-2 xenografts, which have a lower EGFR density than PANC-1, and a 35-fold higher IC50 for CTX-MMAE, treatment with CTX-MMAE at 0.1, 1 or 5 mg/kg led to dose-dependent inhibition of tumour growth." (PMID 32913288, 2020). "As a result, bispecific monobody fusions have been generated for increased avidity and selectivity against tumour tissues by targeting over-expressed receptors IFG-IR and EGFR in the case of Adnectins." (PMID 32143310, 2020). "Alterations in gene copy numbers on the chromosomes where the EGFR and PDGFRA genes are found tended to occur in the early and middle phases of tumour growth, respectively." (PMID 33120534, 2020). "Western blot analysis of tissue collected from mice bearing H1975 EGFR D770_N771insSVD tumours revealed that TAS6417 is able to inhibit EGFR phosphorylation within the tumour, whilst having minimal effect on WT EGFR phosphorylation within the skin tissue." (PMID 31562956, 2020).
tumor (continued). "(b) AEE788 is a dual EGFR and VEGFR Tyrosine Kinase Inhibitor (TKI) studied both in vitro and in vivo for its anti-tumor effect, alone or in combination with chemotherapy (cisplatin or paclitaxel)." (PMID 33302367, 2020). "Studies show ciRS-7 overexpression can activate the EGFR pathway, which is one of the most important targets of NSCLC, to induce tumor cell growth." (PMID 32090067, 2020). "For example, the combined inhibition of EGFR and C-RAF led to complete tumour regression in murine PDAC models and human patient-derived xenografts." (PMID 33008426, 2020). "In this study, we performed in vitro cell experiments to confirm that piperlongumine did have an anti-tumor effect on HCC, which was achieved through the inhibition of EGF/EGFR signaling pathway-induced angiogenesis." (PMID 32379058, 2020). "Similar to the pattern of EGFR activation and PAR2 degradation observed in vivo, EGFR phosphorylation and PAR2 expression were modulated by PLAG in the lung tissues of tumor-implanted mice." (PMID 32121107, 2020). "A common downstream signaling pathway of activated EGFR is the Ras-MAPK (ERK1/2) pathway, which regulates EMT, tumor invasion, and metastasis." (PMID 31597954, 2020). "In the case of CP, PDK1 upregulates the expression of EGFR and inhibition of PDK1/EGFR axis can suppress EMT and malignancy of tumor cells." (PMID 32503307, 2020). "The NT/NTSR1 complex enhances tumour aggressiveness by increasing human epidermal growth factor receptor (HER) expression and activation via the release of specific EGFR, HER2 and HER3 ligands." (PMID 32336282, 2020). "The multi-targeted inhibition of histone deacetylase (HDAC), HER2 and TGFα receptor (epidermal growth factor receptor/EGFR) improved treatment efficacy in vitro and reduced tumor growth in two MPM mouse models." (PMID 32517259, 2020). "The tumor tissue pathological analysis revealed that MGMT promoter was hypermethylated, EGFR was amplified, and PTEN was deleted in the original tumor." (PMID 33390879, 2020). "In our study, the combination of two and three proteins (EGFR, HER4 and EphA3) or the combination of these proteins with CA19–9 was an independent prognostic factor for tumor recurrence." (PMID 32093644, 2020). "In EGFR mutant tumors, wild type to KRAS mutant conversion of the tumor was frequent (30%), while in KRAS mutant tumors, the wild type KRAS subclonality was frequent (30%)." (PMID 32725342, 2020). "Amplifications of EGFR and gain of chromosomes 19 and 20 were strongly prevalent in RTK II, and PDGFRA, CDK4 and MDM2 or MDM4 amplifications were more frequent in RTK I tumours." (PMID 33339831, 2020). "Therefore, PIPKIγi5 down-regulates EGFR signaling and may function as a tumor suppressor." (PMID 33061794, 2020). "Nevertheless, targeted tumor therapies can be restricted by the emergence of resistant tumor cells to BRAF inhibitors and EGFR inhibitors." (PMID 32695658, 2020). "Recently, activated EGFR signaling has been shown to promote EMT, which generates cells with stem-like properties and drives cells to dissociate from the primary tumor and migrate/invade into surrounding tissues." (PMID 31597954, 2020). "Reduction of lymph nodes metastases and serum tumour markers have also been reported in a BM-CUP (positive for Napsin A, TTF-1, and EGFR exon 19 deletion) treated with the EGFR-TKI gefitinib." (PMID 33198246, 2020). "In a preclinical NSCLC in vivo model, AZD4205 treatment inhibited tumor growth and STAT3 activation; these findings were more significant when AZD4205 was administered in combination with the EGFR inhibitor osimertinib." (PMID 33521321, 2020).
tumor (continued). "MET/HGF hyperactivation is also related to resistance to EGFR-TKIs (tyrosine kinase inhibitors); HGF promotes the clonal selection of c-MET amplified tumor subpopulations, which confers them substantial growth advantage and invasive potential." (PMID 32575417, 2020). "In this study, we confirmed that EGFR‐vIII epigenetically silenced ubiquitin‐specific protease 11 (USP11) in vitro and in vivo, which mediated tumour suppression though blocking cell cycle progression." (PMID 31993801, 2020). "The epidermal growth factor receptor (EGFR) family members EGFR and HER2 play pivotal roles in oncogenesis and tumor progression." (PMID 32398965, 2020). "Therefore, the researchers suggested that EGFR may play a role in tumor-induced angiogenesis." (PMID 33302367, 2020). "Immunohistochemistry verified that CRM197 inhibited HB-EGF, p-EGFR, and PKM2 expression in mouse tumor tissues." (PMID 32695675, 2020). "Binding with TGF-β, EGFR, HGFR, IGFR, and other growth factors, decorin weakens their downstream signals and inhibit tumor cell proliferation." (PMID 32825245, 2020). "To exam the vascular density within tumor tissues, we examined the expression of CD31, EGFR, and MVD by IHC staining." (PMID 32181596, 2020). "The GE11 peptide has high affinity for the epidermal growth factor receptor and GE11-positive exosomes that contained the miRNA let-7 were able to prevent tumor growth." (PMID 31114624, 2019). "In addition, we analyzed the expression of EGFR and EMT-related proteins including slug, vimentin, and E-cadherin in murine tumor tissues using immunohistochemical staining, and found that psorachromene may significantly inhibit the expression of EGFR and EMT-promoting proteins." (PMID 31750253, 2019). "In contrast to these tumours (MGG70 and MGG70R), the expression of EGFR and phospho-EGFR was substantially decreased in the post-dacomitinib tumour MGG70RR." (PMID 30644426, 2019). "Signaling pathways triggered by growth factor receptors, including EGFR and PDGFR, contribute to tumor development in GBM and NF-κB plays key roles in these pathways." (PMID 31467533, 2019). "In clonogenic assays, monospecific 177Lu- and 111In-trastuzumab Fab or EGF only killed tumour cells that expressed HER2 or EGFR, respectively, while the bsRICs were able to kill cells that expressed HER2 or EGFR or both receptors." (PMID 31659527, 2019). "AuNPs can be conjugated to epidermal growth factor receptor (EGFR) through an antibody, for targeting tumor cells." (PMID 31179276, 2019). "Pyrotinib directly acts on the tyrosine kinase domain of the HER2 pathway and completely blocks downstream pathways activated by homodimers or heterodimers of EGFR, HER2, and HER4 on the tumor cell membrane." (PMID 31956604, 2019). "This animal showed high Ki67 positivity in the tumor tissue as well as high expression levels of the growth factors HER-2 and epidermal growth factor receptor (EGFR)." (PMID 31676831, 2019). "With ligand combining with EGFR, STAT3 is phosphorylated and promotes tumor cell invasion and poor prognosis of colorectal adenocarcinoma." (PMID 31368612, 2019). "Within the Ras/RTK pathway, epidermal growth factor receptor (EGFR, 30–50% of tumours) and phosphatase and tensin homolog (PTEN, 30%) are the most commonly mutated in GBM, although mutations in NF1 and RAS have also been documented." (PMID 31505839, 2019). "Different from EGFR and BRAF inhibitors, sorafenib, a multi-target antitumor drug, increases PD-L1 expression through inducing tumor hypoxia." (PMID 31258527, 2019).
tumor (continued). "In an effort to discover new bioactive anti-tumor lead compounds, a specific tyrosine phosphatase CDC25B and an Erb family receptor EGFR were selected as drug screening targets." (PMID 31480659, 2019). "Their gene ontology classification evidenced the involvement of the adherence system, intermediate filaments, and actin cytoskeleton in tumor pathogenesis and of elements part of the Wnt, FGF, and EGFR signaling pathways." (PMID 31191748, 2019). "The repression of EGFR/VEGFR- and mTOR-related pathways in concert seemingly reverts processes predominantly responsible for uncontrolled TNBC tumor proliferation." (PMID 31388935, 2019). "To further support the paracrine HB‐EGF/EGFR signaling axis in endothelial cells, we incubated HUVEC cells in CCM from PDAC tumor cells (shControl and shADAM9) for 15 min." (PMID 30556643, 2019). "The results indicated that EGFR, AKT, STAT3, and EZH2 all play a crucial role in promoting cell proliferation and tumor growth in seminal vesicles of TRAMP mice." (PMID 31592235, 2019). "Aberrant expression of EGFR has been observed in multiple malignancies, and activated molecules can irritate the PI3K/Akt and JNK/STAT signaling pathways, which contribute to tumor metastasis." (PMID 31214503, 2019). "For EGFR, ERBB2, and MET gene amplification, we set the absolute copy number ≥6 as amplification for WES with tumor and normal pairs and log2 ratio ≥ 3-fold standard derivation (SD) as amplification for the ctDNA compared with a panel of normals." (PMID 31739500, 2019). "Non-keratinizing NPC is characterized by high expression of EGFR, as well as EGFR gene amplification in pre-clinical NPC models and patients’ tumor samples." (PMID 31114729, 2019). "miR-96 can be considered as one of tumor-inducer and form competing endogenous RNA network with FOXO1 and DUSP1, which affects downstream EGFR signaling." (PMID 31579447, 2019). "Studies on dual blockade of EGFR and c-MET have reported promising anti-tumor activity of combined treatment." (PMID 31308358, 2019). "Further in vivo studies are needed to identify appropriate delivery methods that can efficiently and specifically target EGFR and CXCR7 in tumor cells." (PMID 30935067, 2019). "After that, T-NLC was used in combination with A-NLC (EGFR specific small peptide AR modified NLC), the combined T-NLC and A-NLC exhibited more tumor cell accumulation both in vitro and in vivo." (PMID 30880491, 2019). "However, a growing body of evidence indicates that receptors such as EGFR and Met receptor tyrosine kinases (RTKs) or β1-integrin can remain active within endosomes to provide spatially and temporally restricting signals that contribute to pathway-specific tumor progression." (PMID 31420553, 2019). "EGFR and VEGFR-2 represent promising targets for cancer treatment as they are very important in tumor development as well as in angiogenesis and metastasis." (PMID 32039146, 2019). "Regarding tumor grade, datasets GSE5206 and GSE3538 showed a significant correlation between high EGFR mRNA expression and poor differentiation (cutoff median, p = 0.03; cutoff median = mean, p = 0.02; respectively)." (PMID 30956774, 2019). "In our models, we assume that only EGFR/ERK, p38 and Fas signaling pathways that are disturbed for tumor cells." (PMID 31157216, 2019). "We further found that tumour cell‐intrinsic CTLA4 regulates PD‐L1 expression and cell proliferation via the EGFR pathway." (PMID 30378264, 2019). "We determined that AXL interacted with other molecules, including EGFR and HER3, and maintained survival of tumor cells exposed to osimertinib." (PMID 30651547, 2019). "In order to identify possible mechanisms of resistance to anti-EGFR MoAbs in CRC, we analyzed tumor samples from 21 KRAS/NRAS/BRAF/PIK3CA wt mCRC patients enrolled in the CAPRI-GOIM clinical trial by targeted sequencing." (PMID 31226844, 2019).